SFRP5 (secreted frizzled related protein 5)
Diseases named in the same sentence as SFRP5 in open-access papers (continued):
Sharing a sentence is not in itself a finding about the gene and the disease.
diabetes (28 papers, 2014 to 2025). "In that study, serum sFRP5 concentration was associated positively with arterial stiffness in patients with type-2 diabetes mellitus, possibly representing a compensatory reaction of sFRP5 to metabolic stress during the early development of atherosclerosis." (PMID 32429518, 2020). "SFRP5 suppresses chronic inflammation and can consequently improve insulin sensitivity, highlighting its role as an independent risk factor for type 2 diabetes mellitus (T2DM), with a notably important role in the maintenance of glucose homeostasis." (PMID 29789397, 2018). "SFRP5, a member of the SFRP family, has been linked to several immune-related disorders, including rheumatoid arthritis, psoriasis, and type 2 diabetes mellitus, which are conditions similar to vitiligo." (PMID 38920996, 2024). "The study also included 282 human subjects with type 2 diabetes mellitus who were analyzed by measuring circulating levels of SFRP5 and WNT5A and brachial-ankle pulse wave velocity." (PMID 36984870, 2023). "In the second data, it emerged that in the human population with type 2 diabetes mellitus, the serum concentration of SFRP5 was strongly consistent with the brachial-ankle pulse wave velocity (r = 0.146; p = 0.024)." (PMID 36984870, 2023). "Secreted frizzled-related protein-5 [Sfrp5] has been shown to be an innovative adipose tissue-released hormone which connects overweight to diabetes and is currently known as an anti-inflammatory adipokine." (PMID 36404859, 2022). "Plasma SFRP5 levels were found to be distinctly decreased in obese patients and patients with diabetes, coronary artery disease, and other related diseases." (PMID 36618366, 2022). "In conclusion, SFRP5 plays a protective role in HG induced HUVECs and diabetes mellitus combined with myocardial ischemia." (PMID 35506262, 2022). "Downregulation of miR-124-3p has also been shown to influence the functioning of pancreatic-β-cell via the targeting of secreted frizzled-related protein 5 (SFRP5) in Diabetes mellitus." (PMID 37529096, 2022). "It is important to note that any of the patients of our cohort who presented T2DM neither need pharmacological treatment since it has been reported that treatments for diabetes alter SFRP5 levels." (PMID 34198988, 2021). "The aim of this study was to determine the correlation between serum Wnt5a and Sfrp5 concentrations and glomerular filtration rate in patients with type 2 diabetes mellitus and chronic kidney disease." (PMID 32491086, 2020). "To date, research on the connections among the Wnt5a protein, Sfrp5, and diabetes has mainly focused on adipose tissue, inflammation, and insulin resistance." (PMID 32184820, 2020). "Previous studies of Wnt5a and diabetes focused on islet development, insulin resistance, inflammation, and studies relating the Wnt5a antagonist protein Sfrp5 to islet function." (PMID 32184820, 2020). "Research on the connections between the Wnt5a protein, Sfrp5, and diabetes is mainly concentrated on adipose tissue, inflammation, and IR." (PMID 31097962, 2019). "This review aims to identify the recent progress in the research and development of SFRP5 that can play a role in influencing lipid metabolism, inflammation, and type 2 diabetes mellitus (T2DM)." (PMID 29789397, 2018). "Our results support a role for SFRP5 as a protective factor in the pathogenesis of autoimmune diabetes and facilitate a novel aspect for diabetes research." (PMID 26150852, 2015). "In addition to SFRP5, ApoA‐I, and HDL3‐C, diabetes and high levels of hs‐CRP are risk factors for ISR in AMI patients after PCI." (PMID 40056066, 2025). "In addition, although we provided the role of SFRP5 in HG induced HUVECs and diabetes mellitus combined with myocardial ischemic injury, specific clinical applications still needed corresponding clinical trials." (PMID 35506262, 2022). "The molecular mechanisms of SFRP1, SFRP4, and SFRP5 may have a direct or indirect effect on the development of diabetes." (PMID 35457182, 2022).
diabetes (continued). "Type 2 diabetes mellitus patients showed a decrease in plasma concentrations of SFRP5 which were unfavorably related to the evaluation of the homeostatic insulin resistance model, suggesting that SFRP5 could play a defensive action in the pathogenesis of T2DM." (PMID 33192583, 2020). "Furthermore, plasma SFRP5 has been linked to homeostasis model assessment of insulin resistance (HOMA-IR), uric acid, diabetes duration, and BMI." (PMID 29789397, 2018). "In the population-based KORA study, circulating SFRP5 was independently associated with BMI, HbA1c, systolic blood pressure, HDL cholesterol, eGFR, hsCRP and adiponectin which represent risk factors for type 2 diabetes and diabetes-related cardiovascular diseases." (PMID 28851362, 2017). "The GFR of each individual was estimated and the serum Sfrp5 and Wnt5a levels were subsequently quantified to determine the correlation of these proteins with the clinical evolution of CKD patients with type 2 diabetes mellitus." (PMID 32491086, 2020). "And the presence of CHD was associated with plasma WNT5A (positive) concentrations, plasma SFRP5 (negative) concentrations and plasma WNT5A/SFRP5 ratio (positive) independently of traditional risk factors (hypertension, hyperlipidemia, diabetes and smoking)." (PMID 32004418, 2020). "Moreover, this study only focused on SFRP5, ApoA‐I, HDL3‐C, diabetes, and hs‐CRP, and may have ignored other factors that may affect the development of ISR." (PMID 40056066, 2025). "Notably, presence of diabetes, arterial hypertension, and chronic obstructive pulmonary disease had no influence on serum levels of SFRP5." (PMID 36830849, 2023). "Besides sFRP5, parameters of glucose status: glucose and HOMA-IR, inflammatory markers: IL-6 and CRP showed significant differences between healthy controls and diabetes subjects, but not between subjects with and without DPP4i treatment." (PMID 36056109, 2022). "Previous studies unanimously reported that SFRP5 exerted an anti-inflammatory effect by inhibiting the non-canonical Wnt5a/JNK signaling pathway, therefore playing a key role in repressing the occurrence and development of various diseases including obesity, cardiovascular diseases, and diabetes." (PMID 35506262, 2022).
Insulin resistance (26 papers, 2013 to 2024). Increased resistance towards insulin, that is, diminished effectiveness of insulin in reducing blood glucose levels. "Animal studies have indicated a decrease in the expression of Sfrp5 in obese models, while Sfrp5 deficiency causes insulin resistance, glucose intolerance, and hepatosteatosis." (PMID 39339733, 2024). "Targeted mutation of Sfrp5 in animal models induces insulin resistance, glucose intolerance, and hepatosteatosis when the animals are fed a high-fat diet." (PMID 34371968, 2021). "One study showed that in human adipocytes, SFRP5 impairs insulin sensitivity, whereas associations between blood concentration of SFRP5 and homoeostasis model assessment of insulin resistance (HOMA-IR) vary between studies." (PMID 34184187, 2021). "Wnt member 5a (Wnt5a) and secreted frizzled-related protein 5 (Sfrp5) are proinflammatory proteins associated with insulin resistance and chronic low-grade adipose tissue inflammation." (PMID 32491086, 2020). "In this context, mice deficient in SFRP5 (SFRP5−/−) fed a high-fat diet exhibited higher macrophage-mediated adipose tissue inflammation and insulin resistance respect to wild type mice due to uncontrolled activity of WNT5A." (PMID 33192583, 2020). "They observed that SFRP5‐deficient (SFRP5−/−) mice fed a high‐fat diet showed greater adipose tissue inflammation mediated by macrophage and insulin resistance compared with wild‐type mice due to unrestrained WNT5A activity." (PMID 32004418, 2020). "The cited authors found that lower serum SFRP5 potentiated the association between Wnt-5A and insulin resistance." (PMID 30704061, 2019). "One study showed that loss of functional Sfrp5 mitigated increases in serum leptin levels, as well as the induction of glucose intolerance and insulin resistance after high-fat feeding." (PMID 24465779, 2014). "Accordingly, HFD fed SFRP5 deficient mice Sfrp−/− have insulin resistance and fatty liver along with enhanced inflammatory macrophage accumulation to produce IL-6, TNF-α, and CCL2 suggesting that SFRP5 is an anti-inflammatory adipokine." (PMID 23781214, 2013). "In obese animal models, a significant reduction in SFRP5 expression levels has been observed, and this deficiency may be strongly associated with insulin resistance and adipose tissue inflammation." (PMID 37957661, 2023). "Thus, the possibility that reduced SFRP5 levels may contribute to the state of insulin resistance associated with increasing age and pubertal development cannot be excluded." (PMID 30704061, 2019). "We recently reported a positive association of Sfrp5 with insulin resistance and markers of oxidative stress in mostly overweight and obese Caucasians, indicating that the function of Sfrp5 in humans may be dependent on the subjects' metabolic and inflammatory state." (PMID 24465779, 2014). "It is essential to acknowledge that there are also studies indicating a positive correlation between SFRP5 and insulin resistance, along with other metabolic abnormalities." (PMID 37957661, 2023). "It is postulated that this synergy is attributed to the role of SFRP5 in regulating inflammatory responses and insulin resistance, while the TyG index directly reflects insulin resistance status and lipid health, creating a complementary relationship." (PMID 37957661, 2023). "SFRP5 is a member of the secretory glycoprotein SFRP family that is involved in both insulin resistance and inflammation." (PMID 37957661, 2023). "To investigate the effect of lipid-induced insulin resistance on circulating SFRP5 in vivo, we examined the alterations of serum SFRP5 level during lipid infusion combined with HEC." (PMID 34184187, 2021). "In the same way, SFRP5 knockout mice acquire severe insulin resistance and hepatic steatosis with a greater macrophage accumulation in their adipocytes." (PMID 34948320, 2021). "Data on the role of SFRP5 in insulin resistance stem mainly from experimental studies and are controversial." (PMID 34184187, 2021).
Insulin resistance (continued). "SFRP5, a novel adipokine secreted by the adipocytes has anti-inflammatory effects and reduces insulin resistance." (PMID 32300333, 2020). "Up-regulation of SFRP5 inhibits insulin resistance and inflammation by activating JNK mediated by Wnt in adipocytes and macrophages, thereby providing systemic effects." (PMID 29789397, 2018). "Ample evidence demonstrated that Adipolin/C1qdc2/CTRP12 and SFRP5 could regulate and improve glucose metabolism, inflammation level, insulin resistance (IR), and dyslipidemia." (PMID 37542207, 2023). "These discrepancies underscore the idea that the mechanism through which SFRP5 impacts inflammation and insulin resistance may be influenced by specific medications, individual patient characteristics, and the overall metabolic context." (PMID 37957661, 2023). "In patients with metabolic syndrome (MetS), circulating Sfrp5 concentrations were lower than in control subjects, they progressively decreased as the MetS components increased, and were negatively correlated with HbA1C and insulin resistance (HOMA-IR)." (PMID 34371968, 2021). "The majority of studies suggest a negative association between Sfrp5 and insulin resistance, as indicated by the lower concentrations of Sfrp5 in PCOS women." (PMID 34371968, 2021). "Secreted frizzled-related protein 5 might be a therapeutic target for insulin resistance in obstructive sleep apnea." (PMID 30120048, 2019). "The expression and transcription of SFRP5 have been reported to share a negative association with insulin resistance." (PMID 29789397, 2018). "Our study is in line with previous reports suggesting a protective role of Sfrp5 in the development of type 2 diabetes in mice and with human studies demonstrating an inverse association between circulating SFRP5 and HOMA-IR, a fasting measure of insulin resistance." (PMID 28851362, 2017). "Nevertheless, a limitation of the present study is that we did not examine additional pathways potentially involved in the induction of insulin resistance by Sfrp5, such as activation of the proteasome or the mammalian target of rapamycin complex 1 signaling cascade." (PMID 24465779, 2014). "The mode of action of Sfrp5 in inflammation and insulin resistance might depend on the kind of tissue and defined inflammatory and metabolic circumstances of the site of action." (PMID 24465779, 2014). "In addition, there was a negative relevance between the SFRP5 plasma concentration and insulin resistance in individuals with T2D, and SFRP5 had a protective effect that might act against the mechanism of T2DM pathogenesis." (PMID 37542207, 2023). "Insulin resistance, abnormal metabolism of fat factors [pro-inflammatory adipokines (leptin, resistin, TNF-α), anti-inflammatory adipokine (adiponectin), specific adipokine Sfrp5], and vitamin D deficiency are all possible causes of abnormal blood lipids in visceral obese individuals." (PMID 37674809, 2023). "The positive correlation between SFRP5 with markers of oxidative stress and insulin resistance has been highlighted amongst predominantly overweight and obese Caucasian populations, suggesting that the action of SFRP5 in humans may be affected by metabolic and inflammatory conditions." (PMID 29789397, 2018). "Three studies describe an association of higher SFRP5 levels with type 2 diabetes or insulin resistance in non-diabetic subjects, whereas two studies show the opposite effect, lower SFRP5 levels in subjects with prediabetes or type 2 diabetes in comparison to controls." (PMID 25408147, 2014). "SFRP5 is related to leptin and LGR4 and these two indicators effective of insulin resistance in diabetic patients." (PMID 36404859, 2022). "In spite of the conflicting outcomes regarding the relationship of the SFRP5 levels with insulin resistance and CAD, the majority of up-to-date research supports the beneficial role of SFRP5 in cardiometabolic health." (PMID 34948320, 2021).
Insulin resistance (continued). "Circulating Wnt5a correlated strongly with insulin resistance and hepatic enzymes (SGOT, SGPT), particularly in children with lower circulating Sfrp5 concentrations." (PMID 34371968, 2021). "The present study aims to investigate the levels of leptin, resistin, visfatin, SFRP5, MCP-1/CCL2, and RBP4 as well as their correlations with insulin resistance and clinical parameters of overweight and T2DM in a Vietnamese study group." (PMID 29785210, 2018). "Indeed, SFRP5 expresses itself strongly in WAT relative to other tissues and Also when normoglycemic, insufficient SFRP5 demonstrate insulin resistance and a fatty liver." (PMID 36404859, 2022). "It is well established that SFRP5 is expressed in the WAT of lean mice but downregulated in extremely obese mice, and has been emerged as an anti-inflammatory adipokine to protect against insulin resistance." (PMID 31470850, 2019). "In addition, we also examined the diagnostic potential of resistin/MCP-1, resistin/RBP4, visfatin/MCP-1, visfatin/SFRP5 and MCP-1/RBP4 indexes in insulin resistance/sensitivity and β-cell function." (PMID 29785210, 2018). "In contrast to primary human adipocytes, Sfrp5 did not affect insulin signaling in hSkMC, neither under basal culture conditions nor following MCP-1-induced insulin resistance." (PMID 24465779, 2014).
type 2 diabetes (21 papers, 2012 to 2024). "Here, higher Sfrp5 was inversely associated with multiple risk factors for type 2 diabetes and cardiovascular diseases as well as lower odds of prediabetes/type 2 diabetes suggesting a protective role of Sfrp5 in the development of cardiometabolic diseases." (PMID 30921355, 2019). "We aimed to characterise associations of circulating SFRP5 with cardiometabolic risk factors and prediabetes/type 2 diabetes in a large population-based cohort." (PMID 28851362, 2017). "This is the first study that investigated the association between SFRP5, prediabetes and type 2 diabetes in a large population-based study and controlled for a range of potentially confounding factors." (PMID 28851362, 2017). "In this study, we also investigated the association of serum SFRP5 with multiple cardiovascular risk factors in addition to glycaemia and prediabetes/type 2 diabetes." (PMID 28851362, 2017). "The largest of these studies demonstrated that serum SFRP5 levels are inversely associated with multiple cardiometabolic risk factors, including BMI and type 2 diabetes, thereby confirming the relationship between low SFPR5 levels and cardiometabolic risk factors." (PMID 37504530, 2023). "Clinical studies have found that the level of SFRP5 protein in patients with type 2 diabetes is significantly higher than that of normal people." (PMID 37255814, 2023). "Serum SFRP5 levels were lower in participants with prediabetes or type 2 diabetes [(median (25th; 75th percentile) 48.8 (35.5; 65.7) ng/ml] compared to participants with normal glucose tolerance [55.9 (42.6; 69.6) ng/ml] (P < 0.001)." (PMID 28851362, 2017). "In the subgroup with type 2 diabetes, neither glycaemic control (assessed by HbA1c), duration since the diagnosis of type 2 diabetes nor the type of glucose-lowering medication showed any association with SFRP5 levels (all P > 0.05)." (PMID 28851362, 2017). "Additionally, two studies also reported lower Sfrp5 levels in patients with type 2 diabetes compared to individuals with normal glucose tolerance." (PMID 28851362, 2017). "In particular the study with the opposing result of higher Sfrp5 levels in patients with type 2 diabetes was based on highly selected individuals with optimal glycaemic control (median HbA1c 5.8%) who cannot be considered representative for people with type 2 diabetes in the general population." (PMID 28851362, 2017). "Higher circulating SFRP5 was also associated with lower odds of prediabetes/type 2 diabetes, and this association was independent of BMI." (PMID 28851362, 2017). "Similarly, patients with diabetes mellitus type II have been shown to exhibit increased expression of sFRP5, a Wnt inhibitor, which has been correlated with a decrease in Wnt5a levels." (PMID 27688915, 2016). "Our study found that the serum Wnt5a protein level of newly diagnosed type 2 diabetes patients was significantly increased after the intervention of the glucagon-like peptide-1 receptor agonist compared with before treatment, and the antagonist Sfrp5 was lower than that of the control group." (PMID 37255814, 2023). "Therefore, CTRP12, SFRP5, and IL-6 could be biomarkers for monitoring inflammation, type 2 diabetes, and dyslipidemia." (PMID 37542207, 2023). "However, the role of SFRP5 in type 2 diabetes is still controversial." (PMID 25408147, 2014). "Our study found that the serum Wnt5a protein level of newly diagnosed type 2 diabetes patients was significantly increased after the intervention of the GLP-1RA compared with before treatment, and the Sfrp5 was lower than that of the control group." (PMID 37255814, 2023). "Recently, in humans in a series of cross-sectional and interventional studies, it has been demonstrated that circulating SFRP5 is significantly lower in subjects with both IGT and newly diagnosed type 2 diabetes compared with subjects with normal glucose tolerance." (PMID 24362411, 2014).